LGR6 (leucine rich repeat containing G protein-coupled receptor 6)
Description:
Receptor for R-spondins that potentiates the canonical Wnt signaling pathway and acts as a marker of multipotent stem cells in the epidermis. Upon binding to R-spondins (RSPO1, RSPO2, RSPO3 or RSPO4), associates with phosphorylated LRP6 and frizzled receptors that are activated by extracellular Wnt receptors, triggering the canonical Wnt signaling pathway to increase expression of target genes. In contrast to classical G protein-coupled receptors, does not activate heterotrimeric G proteins to transduce the signal. May act as a tumor suppressor.
Synonyms: VTS20631; FLJ14471; GPCR
Tractability: Small molecule: it belongs to a druggable protein family. Antibody: UniProt places it where antibodies can reach, with high confidence; its Gene Ontology location is reachable by antibodies, with high confidence; UniProt predicts a signal peptide or a membrane-spanning region; the Human Protein Atlas places it where antibodies can reach.
Gene: Protein-coding gene on chromosome 1 (202,193,692 to 202,319,781, forward strand). Ensembl gene ENSG00000133067.
Subcellular location: Cell membrane
Subcellular location (Human Protein Atlas): Plasma membrane; Nucleoplasm
Pathways (Reactome):
Signal Transduction: Regulation of FZD by ubiquitination
Gene Ontology:
Molecular function: protein binding; G protein-coupled receptor activity; heparin binding; Roundabout binding; transmembrane signaling receptor activity; protein-hormone receptor activity
Biological process: positive regulation of cell migration; positive regulation of Wnt signaling pathway; axon guidance; negative chemotaxis; positive regulation of canonical Wnt signaling pathway; G protein-coupled receptor signaling pathway
Cellular component: vesicle; plasma membrane; trans-Golgi network membrane; membrane
Genetic constraint (gnomAD): Loss-of-function variants: 42 observed, 61.31 expected, observed/expected ratio (o/e) 0.69, 90% interval 0.53 to 0.89. The upper end of that interval is the gene's LOEUF score, 0.89, which puts it in group 3 of 6, group 1 being the genes least tolerant of losing a copy. Missense variants: 1,094 observed, 1,223 expected, observed/expected ratio (o/e) 0.89, 90% interval 0.85 to 0.94. Synonymous variants: 533 observed, 543.12 expected, observed/expected ratio (o/e) 0.98, 90% interval 0.91 to 1.05.
Homologues: Orthologues: chimpanzee LGR6 (99% identical), macaque LGR6 (98% identical), rat Lgr6 (90% identical), mouse Lgr6 (90% identical), dog LGR6 (89% identical), guinea pig LGR6 (89% identical), rabbit LGR6 (89% identical), pig LGR6 (82% identical), Caenorhabditis elegans sma-10 (15% identical), Drosophila melanogaster kek3 (14% identical), Drosophila melanogaster Con (12% identical), Caenorhabditis elegans lron-9 (11% identical). Paralogues in human: LGR5 (51% identical), LGR4 (44% identical), LRIG2 (21% identical), LRIG1 (21% identical), LRIG3 (21% identical), TRIL (14% identical), CPN2 (13% identical), CHADL (13% identical), LGI2 (11% identical), LRIT3 (11% identical), LGI1 (11% identical), LRRC24 (11% identical), and 10 more.
Diseases named in the same sentence as LGR6 in open-access papers:
LGR6 is named in the same sentence as 75 diseases in open-access papers, as found by Europe PMC text mining. Sharing a sentence is not in itself a finding about the gene and the disease. The quoted sentences say what the papers report.
ovarian carcinoma (15 papers, 2011 to 2025). A malignant neoplasm originating from the surface ovarian epithelium. "Loss-of-function assays showed that silencing LGR6 repressed the stemness and improved chemoresistance of ovarian cancer cells." (PMID 31193124, 2019). "Luciferase assays and GSEA were used to discern the underlying mechanisms contributing to the roles of LGR6 in ovarian cancer." (PMID 31193124, 2019). "In ovarian cancer, LGR6 has been found to be associated with the development and progression of high-grade serous ovarian carcinoma." (PMID 31193124, 2019). "Kaplan-Meier survival analysis indicated that overexpression of LGR6 was significantly associated with poor progression-free survivals in ovarian cancer patients." (PMID 31193124, 2019). "We mined the COSMIC (Catalogue Of Somatic Mutations In Cancer) database for additional mutations and found that LGR6 is also somatically mutated in cancers of the ovary and pancreas." (PMID 22615920, 2012). "However, the specific mechanism underlying LGR6-induced activation of Wnt/β-catenin signaling in ovarian cancer remains unclear, which requires further investigation in the following work." (PMID 31193124, 2019). "In oncology, LGR6 drives Wnt/β-catenin hyperactivation in ovarian cancer and esophageal squamous cell carcinoma (ESCC), facilitating metastasis and unfavorable prognosis." (PMID 40821817, 2025). "In recent studies, LGR6 not only promotes the initiation and progression of cancers such as lung adenocarcinoma, luminal mammary tumor, and ovarian cancer but also activates the phagocyte immunoresolvent function by binding to MaR1." (PMID 34489551, 2021). "In the present manuscript, our results demonstrated that LGR6 was upregulated in ovarian cancer tissues, which positively correlated with shorter overall and progression-free survival in ovarian cancer patients." (PMID 31193124, 2019). "Consistently, our findings found that silencing LGR6 robustly inhibited Wnt/β-catenin signaling in ovarian cancer cells." (PMID 31193124, 2019). "More importantly, silencing LGR6 improved the chemoresistance of ovarian cancer cells to cisplatin in vivo." (PMID 31193124, 2019). "Collectively, these results indicate that silencing LGR6 abrogates chemoresistance in ovarian cancer cells." (PMID 31193124, 2019). "The pivotal findings of this study provide insights into the functional role of LGR6 in ovarian cancer." (PMID 31193124, 2019). "We further examined the expression levels of LGR6 in one ovarian epithelial cell line, HOSEpiC, and eight ovarian cancer cells, respectively, and found that LGR6 expression was differentially enhanced in ovarian cancer cells compared with that in HOSEpiC." (PMID 31193124, 2019). "Here, we reported that LGR6 was upregulated in ovarian cancer, which positively correlated with poor chemotherapeutic response and progression survival in ovarian cancer patients." (PMID 31193124, 2019). "More importantly, repression of Wnt/β-catenin signaling by LGR6 downregulation inhibited CSC characteristics as well as enhanced the sensitivity of ovarian cancer cells to chemotherapeutics." (PMID 31193124, 2019). "Our results further revealed that silencing LGR6-induced suppression of stemness and chemoresistance in ovarian cancer tissues was dependent on Wnt/β-catenin signaling." (PMID 31193124, 2019). "The analysis result of the ovarian cancer dataset from Kaplan-Meier plotter further revealed that high expression of LGR6 predicted poorer overall and progression-free survival in ovarian cancer patients." (PMID 31193124, 2019). "Consistently, the chemoresistant ability of the LGR6-silenced ovarian cancer cells to cisplatin or paclitaxel were dramatically elevated by S33Y." (PMID 31193124, 2019). "Collectively, our results uncover a novel mechanism contributing to LGR6-induced chemotherapeutic resistance in ovarian cancer, providing the evidence for LGR6 as a potential therapeutic target in ovarian cancer." (PMID 31193124, 2019).
ovarian carcinoma (continued). "TOP/FLASH activity was downregulated in LGR6-silenced ovarian cancer cells compared with that in the vector cells." (PMID 31193124, 2019). "Spheroid formation assay was performed first, and the results showed that silencing LGR6 suppressed spheroid formation ability in ovarian cancer cells." (PMID 31193124, 2019). "First, S33Y significantly reversed activity of Wnt/β-catenin signaling repressed by LGR6 downregulation in ovarian cancer cells." (PMID 31193124, 2019). "In summary, our findings demonstrate that LGR6 promotes the chemoresistance of ovarian cancer cells to cisplatin via activating Wnt/β-catenin signaling pathway." (PMID 31193124, 2019). "Western blot analysis revealed that silencing LGR6 reduced nuclear expression of β-catenin in ovarian cancer cells." (PMID 31193124, 2019). "Silencing LGR6 elevated the activity of caspase-3 and -9 but reduced the expression of Bcl-2 and Bcl-xL in ovarian cancer cells." (PMID 31193124, 2019). "We further determined the clinical significance of LGR6 in different histologic types of ovarian cancer by immunohistochemistry (IHC)." (PMID 31193124, 2019). "Mechanistic investigation further revealed that LGR6 promoted stemness and chemoresistance via Wnt/β-catenin signaling in ovarian cancer cells." (PMID 31193124, 2019). "Mitochondrial membrane potential assay revealed that silencing LGR6 inhibited the mitochondrial potential of ovarian cancer cells after treatment of cisplatin or paclitaxel." (PMID 31193124, 2019). "Cell-viability assays showed that silencing LGR6 decreased the viability of ovarian cancer cells under treatment of cisplatin or paclitaxel." (PMID 31193124, 2019). "Together with the finding that LGR6 is hypermethylated in up to 50% of colon cancer samples and an LGR6 truncation mutant has been identified in ovarian cancer, these data imply that LGR6 functions as tumor suppressor for colon and ovarian cancer." (PMID 22615920, 2012). "Nevertheless, the finding of loss-of-function mutations in cancer cells and promoter hypermethylation strongly argues that LGR6 functions as a tumor suppress in colon and ovarian cancer." (PMID 22615920, 2012). "Based on these data, it is suggested that LGR6 plays the role of a tumor suppressor in colon and ovarian cancer." (PMID 22615920, 2012). "Collectively, our results determine the oncogenic role of LGR6 in ovarian cancer." (PMID 31193124, 2019). "We further investigated the effects of LGR6 on the chemoresistance of ovarian cancer cells in vivo." (PMID 31193124, 2019). "Importantly, inhibition of CSC-like phenotypes by LGR6 downregulation dramatically improved the chemoresistance of ovarian cancer cells to cisplatin and paclitaxel." (PMID 31193124, 2019). "We first constructed stable LGR6-downexpressing cell lines by endogenously knocking down LGR6 via retrovirus infection in SK-OV-3 and Caov-3 cells that expressed the highest levels of LGR6 in all ovarian cancer cells." (PMID 31193124, 2019). "Similarly, silencing LGR6 dramatically enhanced the apoptosis rate of ovarian cancer cells treated with cisplatin or paclitaxel." (PMID 31193124, 2019). "The CD133+ population of ovarian cancer cells was repressed by silencing LGR6 via flow cytometry." (PMID 31193124, 2019). "Thus, our results provide a novel finding that LGR6 promotes stemness and chemoresistance via activating Wnt/β-catenin signaling in ovarian cancer." (PMID 31193124, 2019). "In this study, our results showed that silencing LGR6 repressed stemness in ovarian cancer cells." (PMID 31193124, 2019). "Therefore, our results in combination with other studies suggest that LGR6 may serve as a novel therapeutic target in the treatment of chemoresistant ovarian cancer." (PMID 31193124, 2019). "However, the clinical significance and biological functions of LGR6 in ovarian cancer remains unclear." (PMID 31193124, 2019).
ovarian carcinoma (continued). "Thus, better identification of the underlying mechanism responsible for the pro-chemoresistance role of LGR6 in ovarian cancer will enhance our understanding for the chemoresistance in ovarian cancer, which will facilitate the development of novel therapeutic target against ovarian cancer." (PMID 31193124, 2019). "Thus, our results indicate that LGR6 might be used as a potential therapeutic target in ovarian cancer." (PMID 31193124, 2019). "Functional assays in vitro and animal experiments in vivo were carried out to explore the effect of LGR6 on cancer stem cell (CSC) characteristics and chemotherapeutic responses in ovarian cancer cells." (PMID 31193124, 2019). "Similarly, LGR5 and LGR6 are two members of the leucine rich repeat (LGR) containing GPCRs family and are expressed on the surface of ovarian cancer tissues." (PMID 40836974, 2024). "In addition, silencing LGR6 not only inhibited CSC-like phenotypes, but also attenuated the chemoresistance of ovarian cancer cells in vitro and in vivo." (PMID 31193124, 2019). "Furthermore, functional experiments showed that silencing LGR6 inhibited CSC properties and attenuated chemoresistance in ovarian cancer cells via inactivating Wnt/β-catenin signaling." (PMID 31193124, 2019). "Therefore, our findings unravel a novel mechanism by which LGR6 promotes the CSC characteristics and chemoresistance in ovarian cancer cells." (PMID 31193124, 2019). "Furthermore, LGR6 belonged to the LGR family, which could activate the Wnt signaling pathway in ovarian cancer." (PMID 34489551, 2021). "However, the clinical significance and functional role of LGR6 in ovarian cancer remains not reported yet." (PMID 31193124, 2019).
breast cancer (8 papers, 2016 to 2023). A primary or metastatic malignant neoplasm involving the breast. "This identified thirty-one unique genes, of which five have previously been associated with breast cancer (LGR6, NR3C2, LOC105377563, CTNNA3, PRIM1)." (PMID 37345113, 2023). "A good example is a recent study that proved that cells positive for leucine-rich repeat-containing G-protein coupled receptor 6 (Lgr6), which is expressed in LCs and BCs during the early stages of tumorigenesis, contributed to mammary tumor progression." (PMID 35052683, 2021). "After FDR correction, four of these genes were individually significantly associated with disease-free survival, including the steroidogenic enzyme CYP11A; LGR6, a WNT regulator and implicated in breast cancer; and PRR7, a central regulator of CLOCK." (PMID 30120411, 2019). "In both breast cancer models, 100% of Lgr6+ cell-derived tumor cells stained positive for K8." (PMID 36140088, 2022). "Lgr6+ cells were therefore potent tumor-initiating cells for luminal mammary tumors." (PMID 36140088, 2022).
colon cancer (6 papers, 2012 to 2025). "Out of 37 colon cancer samples randomly selected for sequencing, three mutations (299–300insGRS, G725C, and P928H) in LGR6 were found, with the mutation P928H being homozygous." (PMID 22615920, 2012). "In the very first sequencing of total exons from breast and colon cancer samples, LGR6 was found to be one of the commonly mutated genes in colon cancer with three mutations found in a total of 37 cases." (PMID 22615920, 2012). "LGR6 was found as one of the novel genes mutated in colon cancer through total exon sequencing and its promoter region is hypermethylated in 20–50% of colon cancer cases." (PMID 22615920, 2012). "More importantly, LGR6 was found to be one of the commonly mutated genes in a group of colon cancer samples that were sequenced by whole-exon sequencing." (PMID 22615920, 2012). "Moreover, LGR6 is implicated in the growth and proliferation of several cancer types, including gastric and colon cancer and is also attributed with cancer therapy resistance." (PMID 38715790, 2024). "Number of LGR6(+) and LGR6(-) colon cancer patients in different TNM stages divided into different patients groups." (PMID 38715790, 2024). "Leucine-rich repeat containing G protein-coupled receptor 6 (LGR6) is a member of the rhodopsin-like seven transmembrane domain receptor superfamily and mutations in this gene have been reported in colon cancer tissue and gastric carcinoma." (PMID 24708840, 2014). "A follow-up analysis showed that LGR6 is hypermethylated in ∼50% of colon cancer, suggesting that LGR6 functions as a tumor suppressor." (PMID 22615920, 2012). "To gain a better understanding of the function of LGR6 in Wnt/β-catenin signaling and oncogenesis, we also evaluated the activity of the different LGR6 mutants identified in colon cancer." (PMID 22615920, 2012). "An independent, transcriptome-wide approach also found that the promoter region of LGR6 is hypermethylated in ∼20% of colon cancer cases." (PMID 22615920, 2012). "To understand potential roles and mechanisms of LGR6 in oncogenesis, we profiled a panel of colon cancer and uterine cancer cell lines for expression levels of LGR4–6 and RSPO1–4." (PMID 22615920, 2012). "A transcriptome-wide approach showed that LGR6 is hypermethylated in the promoter region in ∼20% of colon cancer, and a follow-up study found hypermethylation in up to 50% of colon cancer samples depending patient ethnicity." (PMID 22615920, 2012). "In the present study we determined the affinity and potency of LGR6 for RSPO1–4 in potentiating Wnt/β-catenin signaling, and characterized the activity of three mutations identified in colon cancer samples." (PMID 22615920, 2012). "With the finding that LGR6 functions as a receptor of RSPOs to potentiate Wnt/β-catenin signaling, we set out to determine the activity of the three mutants identified in colon cancer by comparing them with LGR6 WT." (PMID 22615920, 2012). "LGR6 mRNA levels were determined in 370 half lymph nodes of 121 colon cancer patients." (PMID 38715790, 2024). "The aim was to investigate whether the stem cell marker LGR6 has prognostic value in colon cancer, alone or in combination with the prognostic biomarkers CEA and CXCL16." (PMID 38715790, 2024). "Correlations between levels of PRSS3 and PRSS22 mRNAs and CEA, CXCL16, CXCL17, GPR35 V2/3, LGR5, LGR6 and KLK6 mRNA levels in lymph nodes of colon cancer patients." (PMID 40909962, 2025). "Correlations between LGR6 mRNA expression levels and expression levels of LGR4, LGR5, CEA and CXCL16 mRNAs in lymph nodes of colon cancer patients." (PMID 38715790, 2024). "To examine the effect of LGR6 on growth and migration of cancer cells, we attempted to overexpress LGR6 WT and insGRS mutant in SW620 cells which have relative low expression of LGR4–6 and are routinely used as a model of colon cancer studies." (PMID 22615920, 2012).
colon cancer (continued). "We previously studied mRNA biomarkers that correlated with poor prognosis in colon cancer (CC) patients, such as leucine-rich repeat-containing G protein-coupled receptors 5 and 6 (LGR5 and LGR6), as well as C-X-C motif chemokine ligands 16 and 17 (CXCL16 and CXCL17)." (PMID 40909962, 2025). "However, the binding affinity and functional response of LGR6 to R-spondins, and the activity of colon cancer mutants of LGR6 have not been determined." (PMID 22615920, 2012).